IL6 (interleukin 6)
Diseases named in the same sentence as IL6 in open-access papers (continued):
Sharing a sentence is not in itself a finding about the gene and the disease.
breast cancer (continued). "At present, the application of IL-6/IL-6R/gp130 blockers as anti-cancer agents has not been studied broadly, and to an even lesser extent for breast cancer." (PMID 26840088, 2016). "For example, IL-1 and TGF-β are expressed in breast cancer, and regulate VEGF and IL-6 expression." (PMID 27283985, 2016). "In breast cancer, autophagy inhibition through ATG7 or Beclin1 knockdown altered IL-6 secretion." (PMID 27933272, 2016). "Other inflammatory/immune-stimulating reagents, including lipopolysaccharide (LPS), Pam3Cys (Pam), peptidoglycan (PGN), CpG, and bleomycin (BLM), did not induce IL-6 expression in either MCF7_Cont or MCF7_TG2 breast cancer cells." (PMID 27609180, 2016). "The critical challenges will be to identify which candidates will most effectively repress IL-6 signaling in breast cancer without adverse effects." (PMID 26840088, 2016). "Since IL-6/STAT3 is also an important mediator of the breast cancer cell-MDSC positive signaling loop, targeting key molecules in the IL-6/STAT3 pathways may be a promising therapy for recurrent and drug resistant breast cancers." (PMID 27609180, 2016). "In addition, IL-6-driven PGRN expression was also confirmed in lung, cervical and breast cancer A549, HeLa and MCF-7 cell lines." (PMID 26879559, 2016). "Unlike inflammatory cells, IL-1β stimulation did not lead to IL-6 production, and the overexpression of TG2 alone did not lead to IL-6 production in luminal-type breast cancer cells." (PMID 27609180, 2016). "Although pro-inflammatory cytokines such as IL-1β and TNFα induce IL-6 production from innate immune cells during acute inflammation, this is not the case in human breast cancer cells." (PMID 27609180, 2016). "Additionally, PAC suppressed the expression/secretion of 2 important cytokines IL-6 and MCP-1, and consequently inhibited the paracrine procarcinogenic effects of breast cancer cells on breast stromal fibroblasts." (PMID 27465411, 2016). "Macrophage secretion of pro-inflammatory cytokines IL-6 and TNF-α, which increase MDSC accumulation, was also reduced by WA, additionally WA delayed tumor progression with reduction of the accumulation of G-MDSCs in 4T1 mammary carcinoma bearing mice." (PMID 27886105, 2016). "The present study suggested that FN1, IL6 and FOS may be potential targets in the development of treatments for breast cancer." (PMID 25824986, 2015). "For example, IL-6/Notch-3 signaling increases CAIX expression and stimulates breast cancer cell invasion and HER2+ and triple negative breast cancers which express CAIX are associated with poor prognosis and high levels of early metastases to bone, lung and brain." (PMID 26259239, 2015). "Accumulating evidences showed that IL-6 expression is mainly controlled by MAPK pathway, and sustained activation of MAPK pathways was observed in response to lapatinib resistance in HER2-positive breast cancer cells." (PMID 26513016, 2015). "In this study, we found that that IL6 and CCL5 gene expression are basal breast cancer specific." (PMID 26173622, 2015). "The pro-inflammatory cytokines IL-6 and IL-8 were expressed at both protein and mRNA levels and only in the TN breast cancer cells but not the ER+ breast cancer cells." (PMID 26392082, 2015). "At the same time, IL6 mRNA was not highly expressed in luminal breast cancer, but enriched in basal subtype." (PMID 26173622, 2015). "The data show that all the breast cancer cell lines express varying levels of IL-6, CAP1 and IL-6R, whereas no expression of resistin is observed either at the protein or transcript level in any of the cell lines (data not shown)." (PMID 25868978, 2015). "Moreover, miR-146b inhibits NF-κB-dependent production of IL-6, subsequent STAT3 activation, and IL-6/STAT3-driven invasion and migration in breast cancer cells." (PMID 26697428, 2015).
breast cancer (continued). "Indeed, an expression analysis of various breast cancer cell lines revealed that SRF, YAP/TAZ and IL6 are all upregulated in BLBC cell lines compared with other types of breast cancer." (PMID 26671411, 2015). "Finally, we show that this high SRF expression enables YAP to more efficiently induce IL6 and stemness in BLBC compared with luminal-type breast cancer." (PMID 26671411, 2015). "Mammospheres (MS) from node invasive breast carcinoma tissues express IL-6 mRNA at higher levels than MS from matched non-neoplastic mammary glands." (PMID 25881039, 2015). "In addition, during platelet aggregation by breast cancer cells, platelet-derived lysophosphatidic acid (LPA) induces the release of IL-6 and IL-8 from breast cancer cells, which eventually lead to osteoclastic activation and bone resorption." (PMID 25147739, 2014). "Table-IV illustrates that the highest value of TPA and IL-6 was detected in breast cancer patients with stage IV and the lowest value was detected in those with stage I. There was a significant difference among the 4 stages of breast cancer regarding TPA and IL-6 serum levels." (PMID 25225536, 2014). "Proteomic analysis of MDA231 CM identified IL-6 as a cytokine regulated by ezrin (data not shown) and the IL-6/Stat3 signaling loop has been reported to promote angiogenesis and metastasis in breast cancer." (PMID 25231728, 2014). "It has been shown in vitro that mesenchymal stem cell-secreted IL-6 and VEGF may act as paracrine factors to sustain breast cancer cell migration." (PMID 25514409, 2014). "Moreover, several studies showed a statistical correlation between persistent fatigue and high levels of proinflammatory markers (IL-1ra, IL-6, and sTNT-RII) in breast cancer survivors." (PMID 24800238, 2014). "Additionally, SDC1 expression coordinates β-integrin dependent and interleukin-6 (IL-6) dependent cell functions, such as cell adhesion, migration, and resistance to irradiation, in MDA-MB-231 breast cancer cells." (PMID 25140302, 2014). "Therefore, the association between radiotherapy and memory function impairment might be explained partially by hippocampal inflammation caused by the elevation of plasma IL-6 levels, while adjuvant chemotherapy did not influence the hippocampal volume in breast cancer survivors 26,43." (PMID 24756915, 2014). "Microarray analysis comparing the populations in which the reporter construct is active versus inactive showed that positive cells expressed higher mRNA levels of cytokines (IL-8, IL-6, TNF) and genes (such as ATF3, SNAI2, and KLF6) previously related with the CSC phenotype in breast cancer." (PMID 25414831, 2014). "The mean serum levels of both TPA and IL-6 in the breast cancer patients who received 6 cycles of chemotherapy were significantly lower than their levels in the breast cancer patients who did not received chemotherapy yet." (PMID 25225536, 2014). "Likewise, IL-6 promotes EMT in breast cancer cells, and SNAIL can induce IL-6 expression in keratinocytes." (PMID 24606538, 2014). "IL-6 secretion has been reported to modulate the inducible formation of breast CSCs and their dynamic equilibrium with non-stem cancer cells and recombinant IL-8 increased mammosphere formation and the ALDEFLUOR-positive population in breast cancer cell lines." (PMID 25414831, 2014). "Furthermore, comparison of the basal subtype of breast cancer and the mesenchymal subtype of glioblastoma ASNs shows that an ASN in the vicinity of IL6 is conserved across the two subtypes." (PMID 23368093, 2013). "Additional studies indicate that oncogenic transformation of breast cancer cells leads to chronic activation of NF-κB required to upregulate Lin-28B and downregulate the negative microRNA regulator of IL6, Let-7a." (PMID 23935876, 2013).
breast cancer (continued). "We hypothesized that human plasma, tumor spheroid culture, and exposure to pro-inflammatory cytokines such as IL-6 and TNF-α could induce robust interactions between metastatic breast cancer cells in circulation and the inflamed endothelium." (PMID 23372803, 2013). "IL-19 induces IL-1β, IL-6, TGF-β, and MMP-2 in breast cancer cells." (PMID 23710200, 2013). "Furthermore, LLL12 inhibited Twist1, Notch-1, and Notch-3 expression in ALDH+ breast cancer stem-like cells, which have recently been reported as STAT3 or Interleukin-6 target genes." (PMID 24376586, 2013). "Because stimulation with IL-6 induces IL-19 expression, there may be positive feedback between IL-6 and IL-19 that elicits the STAT3 signal and the progression of breast cancer." (PMID 23710200, 2013). "In our previous study, orthotopically grafted human breast cancer cells expressing high levels of IL-6, but not those with low levels of IL-6, spontaneously metastasized to the lung and liver in immunocompromised NOD/scid/γc-deficient (NOG) mice." (PMID 24021059, 2013). "Among them IL-6, TGF-β and IGF-1 might contribute to the development of brain metastasis in breast cancer cells." (PMID 24324647, 2013). "Moreover, a positive correlation exists between the expression levels of IL-1alpha, IL-6, IL-8 and the CD44(+)/CD24(-/low) population in breast cancer cell lines." (PMID 24392029, 2013). "Specifically, higher levels of proinflammatory cytokines, such as interleukin-6 (IL-6), have been found in depressed and fatigued breast cancer survivors in comparison with controls without these symptoms." (PMID 22830048, 2012). "Besides that, IL-6 is known to promote, together with TGF- β, naive T cells differentiation into Th17 cells, which are found in greater quantities in mice as breast cancer progresses, reaching their highest levels at the later stages of the disease." (PMID 22827934, 2012). "CRP estimation does not seem to be very useful in evaluating the patient with breast cancer, though its level correlates with that of IL-6." (PMID 21294915, 2011). "Focusing on breast cancer patients, 3 prognostic factors remained independently predictive of overall survival: PS >1 (HR = 2.08 [95% CI, 1.30-3.35]), LDH >600 U/L (HR = 2.47 [95% CI, 1.56-3.92]) and IL-6 >8 pg/mL (HR = 1.83 [95% CI, 1.17-2.86])." (PMID 21406082, 2011). "PGE2 further enhanced the tumor promoting properties of fibroblasts by increasing secretion of IL-6, which was necessary, but not sufficient, for expansion of breast cancer stem-like cells." (PMID 21957456, 2011). "Breast cancer cells with high TG2 levels (cont_MB231) showed rapid growth of primary tumor masses in the mammary fatpads compared with TG2-knocked-down cells (shTG2_MB231#1) and IL-6-knocked-down cells (shIL-6_MB231#6)." (PMID 21967801, 2011). "The growth inhibition of human breast carcinoma cells and tumors could be related to the concomitant down-regulation of IL-6, IL-8, and TNF-α in breast carcinoma cells by these drugs." (PMID 21345194, 2011). "In non-CNS diseases, high serum IL-6 levels have been correlated to poor survival of breast cancer, are thought to be proatherogenic, and are strong predictors of mortality in patients with end-stage renal disease." (PMID 20222971, 2010). "In addition, we found that changes in serum IL-1β and IL-6 levels correlated with response to therapy, identifying two possible biomarkers for assessing the effectiveness of anti-VEGF therapy in breast cancer patients." (PMID 19888452, 2009). "Because overexpression of miR-146a/b in human MDA-MB-231 breast cancer cells, reduced thelevels of secreted IL-6 and IL-8 andsince IRAK1 is a key mediator of the expression of IL-6 and IL-8, we comparedthe basal levels of secreted IL6 and IL8 in control and miR-146a/boverexpressing HCA2 cells." (PMID 20148189, 2009). "Unlike MSC-supported ERα-positive breast cancer cells, however, Skov-3 ovarian cancer cell growth is enhanced by IL-6." (PMID 19352430, 2009).
breast cancer (continued). "These also confirmed MDA-MB-231 breast cancer cells secrete much higher levels of IL-6 than immortalized MCF-10A breast cells (data not shown)." (PMID 18939993, 2008). "Understanding how IL-6 and other soluble factors may lead to STAT3 activation via the tumor microenvironment will provide new therapeutic regimens for breast carcinomas and other cancers with elevated p-STAT3 levels." (PMID 18939993, 2008). "Our studies have revealed a prominent and non-redundant role for IL-6 in driving Stat3 activation in breast cancer." (PMID 17531096, 2007). "Polymorphisms within key interleukin genes (IL1A, IL1B, IL1RN, IL4R, IL6 and IL10 do not appear to play a significant overall role in breast cancer susceptibility or severity." (PMID 16842617, 2006). "In this report, we show that ERα transrepresses the expression of the proinvasive gene interleukin 6 (IL-6) in ERα-negative MDA-MB-231 breast cancer cells stably overexpressing ERα." (PMID 14970864, 2004). "Notably, sEV TGF‐β+ did not significantly affect the closely related bone morphogenetic protein (BMP)‐SMAD1/5 signalling in breast cancer cells, nor did it impact the interleukin 6 (IL‐6)/signal transducer and activator of transcription 3 (STAT3) signalling." (PMID 40091448, 2025). "IL-6 activated STAT3-driven metastasis by co-opting ER-FOXA1-STAT3 enhancers metastasis, suggesting that targeting IL6/STAT3 may have clinical potential in ER+ breast cancer." (PMID 40906676, 2025). "Additionally, there was a reduction in serum IL-6 levels in both head and neck cancer patients (pre-PBMT = 94.10 ± 27.17 pg/mL; post-PBMT = 17.30 ± 2.676 pg/mL; p = 0.0307) and breast cancer patients (pre-PBMT = 99.48 ± 21.74 pg/mL; post-PBMT = 26.93 ± 6.813 pg/mL; p = 0.0190)." (PMID 40172371, 2025). "TNBC cells expressing oncogenic multiple copies in T cell malignancy 1 (MCT-1) induces IL-6 via IL-6R and promotes macrophage polarization into M2-like macrophages while silencing MCT-1 and blocking IL-6R by tocilizumab, reducing IL-6R expression and macrophage polarization in breast cancer." (PMID 39858015, 2025). "A very recent study identifies IL-6 as a target gene in the non-canonical Notch activation pathway in breast cancer cells; in fact, the activation of the IL-6/JAK/STAT molecular axis in breast cancer cells has been shown to be mediated by IKKα/IKKβ of the NF-κB signaling cascade." (PMID 40429321, 2025). "This may reflect the down-regulation of IL-6 by estrogen and is consistent with early reports of IL-6 mRNA in basal-like breast carcinoma tissues, but not in ductal breast carcinoma." (PMID 40597443, 2025). "There are currently no FDA-approved IL-6/IL-6R/GP130 inhibitors for the treatment of breast cancer." (PMID 39768178, 2024). "Functional analyses indicated that IgE-mediated antigen stimulation did not elicit classic Ca2+ flux in breast cancer cells as seen in the respective species’ MCs; however, FcεRI crosslinking could stimulate IL-6 production from the T-47D derivatives." (PMID 39195287, 2024). "Furthermore, our data indicated that breast cancer patients who do not respond to chemotherapy present higher IL-6 mRNA expression levels, while non-responder colorectal cancer patients have higher IL-6 and IL-8 mRNA expression levels." (PMID 39336151, 2024). "MDSCs in breast cancer induce IL-6-dependent STAT3 phosphorylation and NOTCH activation via nitric oxide (NO), resulting in prolonged STAT3 activation, which enhances the stem cell-like properties of breast cancer stem cells and inhibits T-cell activation to promote tumor formation." (PMID 38609997, 2024). "Indeed, major gene candidates were identified including IL6, VEGFA and MFGE8 that may play important role in the regulation of TME in breast cancer." (PMID 37975220, 2024).
breast cancer (continued). "However, prolonged incubation (12 and 24 h) of PPMPs and MDA-MB-231 and MCF-7 accelerated the cell cycle and increased the expression of TMBIM6, AP2M1, and PTP4A2 genes and interleukin 6 (IL-6), while the level of the FTH1 transcript decreased in breast cancer cells." (PMID 39518141, 2024). "When EVs derived from highly metastatic 4THM (4T1 heart metastases) murine breast cancer are infused into mice bearing less metastatic EMT6 breast cancer tumors, the EMT6 tumors also become highly metastatic, a process thought to be facilitated through the enhanced secretion of IL-6." (PMID 37025182, 2023). "Comparative analysis of the VEGF/IL-6 ratio during treatment of patients with IBC was higher vs. IIIB stage breast cancer without edema (1.4 vs. 0.7), indicating the aggressiveness of the tumor process and confirmed by an objective response to treatment (regression<30%)." (PMID 36873124, 2023). "GSEA demonstrated that 4T1 breast cancers could still activate the IL-6 signaling and inflammatory response in the absence of Saa1-2 genes, suggesting a subtle or negligible contribution of Saa1-2 to the liver transcriptome in our experimental settings." (PMID 36817472, 2023). "Moreover, obese bASCs have an increased secretion of IL6, which has been shown to trigger cancer cell proliferation by activating the JAK/STAT3, ERK1/2 and STAT3/NFĸB pathways in multiple cancer entities including breast cancer." (PMID 36710348, 2023). "Some studies indicate that immune cells and CAFs secrete IL-6 to activate JAK/STAT3 and PI3K/AKT signaling pathways in tumor cells, which results in the degradation of ERα through the ubiquitin protease pathway, leading to tamoxifen resistance in breast cancer." (PMID 37900137, 2023). "In agreement with the majority of these studies, in our cohort of breast cancer survivors on AIs, depressive symptoms were significantly and positively correlated with CRP and IL-6 with similar, albeit non-significant patterns of associations noted for anxiety and perceived stress." (PMID 36717689, 2023). "In addition, CAAs can also secrete chemokine ligand 2 (CCL2), chemokine ligand 5 (CCL5), and interleukin-1β (IL-1β), Interleukin-6 (IL-6), tumor necrosis factor-α (TNF-α), vascular endothelial growth factor (VEGF) and leptin, which can promote the invasion and metastasis of breast cancer." (PMID 37305043, 2023). "In this study, we did not investigate whether changes in IL6/JAK/STAT3 and OXPHOS signaling explain the increased risk of mammary cancer recurrence in socially isolated rats." (PMID 36980301, 2023). "The identification of a feedback activation loop between IL-6 signaling and nuclear METTL3 function, which can be blunted by aspirin and nicotinamide co-treatment, unravels a critical interplay between inflammatory/oncogenic insults and RNA epigenetic state, which expedites breast cancer metastasis." (PMID 36289222, 2022). "However, the application of IL-6/IL-6R blockers as anti-cancer agents has not been proved intensively in cancers including breast cancer." (PMID 35924148, 2022). "Further, the role of STAT-3 pathway in IL-6 mediated CSC enrichment in breast cancer was confirmed by using Stattic, a STAT-3 inhibitor, and it was observed that pre-treatment with Stattic attenuated activated macrophage derived IL-6 mediated CSC enrichment in breast cancer." (PMID 35300689, 2022). "Similarly, where mammary tumour growth was suppressed by 52% in mice that were subjected to stretching exercise compared to non-stretching mice, IL-6 was upregulated within tumours." (PMID 35359426, 2022). "Furthermore, NDR1 might function as a hub to modulate IL-6, TNF-α or Wnt3a induced activation of Notch1 signaling pathway and enrichment of breast cancer stem cells." (PMID 35508987, 2022).